INS (insulin)
Diseases named in the same sentence as INS in open-access papers (continued):
Sharing a sentence is not in itself a finding about the gene and the disease.
insulinoma (continued). "Overexpression of SELENOS was shown to protect Min6 β-cells, a mouse insulinoma cell line, from oxidative stress-induced apoptosis, suggesting that SELENOS could be important for insulin secretion and insulin sensitivity." (PMID 38172976, 2024). "The insulin pattern in patients with insulinomas might be affected by the presence of high calcium and PTH, as an additional standpoint of the strong interplay of PTH/calcium/insulin." (PMID 38928056, 2024). "They suggested that contradictory levels of insulin and C-peptide should not exclude making a diagnosis of insulinoma." (PMID 39161528, 2024). "Interestingly, when testing miR-129-2 transfection in the insulinoma cell line, we confirmed a decrease in the expression of TMEM219, but more remarkably we detected an increase in MKI67 and Insulin mRNA levels." (PMID 38318298, 2024). "Potential mechanisms include decreased gluconeogenesis due to the destruction of liver parenchyma by large tumors or excess insulin production from non-islet cell tumors such as insulinomas." (PMID 39149633, 2024). "Our study showed that insulin release from the INS-1 832/3 rat insulinoma cell line did not change when cells were treated with different concentrations of adropin, regardless of glucose stimulation." (PMID 39337311, 2024). "Additionally, in insulinoma cells, exposure to PEMF attenuated insulin secretion by affecting calcium influx through calcium channels, suggesting metabolic and physiological effects of PEMF stimulation." (PMID 39201538, 2024). "As a consequence, we assessed insulin secretion by rat insulinoma INS-1 cells and determined whether BBLE increases insulin secretion more than BLE." (PMID 39338524, 2024). "Here, we used a mouse insulinoma MIN6 β-cell culture model to assess the efficacy, cytotoxicity, and insulin-suppressive effects of simvastatin and pravastatin in the presence of palmitic, linoleic, and oleic acids cocktail to mimic mixed lipids challenge in a biologically relevant setting." (PMID 39544235, 2024). "In each pancreatic tumor, we observed a pancreatic ductal cancer that was CEA positive (data not shown), and an insulinoma that was insulin positive and CEA negative (data not shown)." (PMID 37247123, 2023). "For example, in a mouse insulinoma cell and in the stem cells of individuals both having mutant Wfs1 gene, administration of 4-PBA decreased the levels of UPR components and suppressed the ER stress and increased the insulin content in these cells." (PMID 36725880, 2023). "All three of the insulinomas, in which the insulin staining was considered weak, also lacked the expression of GLP-1R." (PMID 37894845, 2023). "To test whether enhanced expression of Trpm7 in β cells induces insulin secretion, we used cultured MIN6 mouse insulinoma cells as an in vitro model." (PMID 36574297, 2023). "In conclusion, we report a case of insulinoma in which postpartum hypoglycemic coma prompted detailed examination and diagnosis of the disease; SACST permitted localization and successful resection of a small insulin-producing tumor in the pancreas." (PMID 37563593, 2023). "Insulinoma is a functional tumor of pancreatic beta cells, characterized by insulin secretion independent of blood glucose concentration." (PMID 37194422, 2023). "If GADA is absent, a β cell antibody panel (insulin autoantibody, IAA; islet cell antibody, ICA; insulinoma-associated protein 2 antibody, IA-2A and zinc transporter 8 autoantibody, ZnT8A) should be tested." (PMID 37554766, 2023). "Finally, the canINS cell line was isolated from a dog with an insulinoma and has been noted for its ability to maintain cancer stem cell (CSC) populations and insulin secretion, although this is limited to certain culture methods." (PMID 37568572, 2023).
insulinoma (continued). "Insulin production has been successfully silenced at the post-transcriptional level using RNA interference in the mouse pancreas or human insulinoma cells, but neither study assessed downstream cellular or metabolic consequences." (PMID 37068109, 2023). "In this study, we have endeavored to conduct a large-scale investigation of candidate genes possibly modulating insulin secretion, which had been identified by comparing two sets of MIN6 insulinoma cell sublines, 3 highly responsive and 3 with mildly lowered glucose-responsiveness." (PMID 37024560, 2023). "In previous work, the miR-216a knockout mouse was reported to have defects in insulin secretion in the context of chronic high-fat diet, and miR-25 has been described as a negative regulator of insulin synthesis in INS-1 cells, a rat insulinoma cell line." (PMID 36757889, 2023). "No other β cell antibodies (insulin autoantibody, IAA; islet cell antibody, ICA; and insulinoma-associated protein 2 antibody, IA-2A) were positive." (PMID 37554766, 2023). "Menin knockdown concomitantly decreased the mRNA expression of both MAFA and β-cell differentiation markers (INS, GCK, SLC2A2, and PDX1) while increasing tumor proliferation, indicating that altered menin expression disrupts the MAFA differentiation pathway in insulinoma." (PMID 35406570, 2022). "High C-peptide and insulin levels indicate that endogenous hypoglycemic agents such as sulfonylureas and insulinoma should be ruled out." (PMID 35758364, 2022). "In the situation of a high insulin level combined with a low glucose concentration HOMA-Beta would theoretically get a negative value, although the secretory capacity of beta cells is high in this situation (e.g. in insulinoma or nesidioblastosis)." (PMID 36271244, 2022). "General demographic and clinical characteristics; hemoglobin A1c (HbA1c), insulin and C-peptide concentrations; and the results of 2-h oral glucose tolerance tests (OGTT) were recorded, and a logistic regression model predictive of insulinoma was determined." (PMID 35916979, 2022). "The insulinoma β-TC6 cells encapsulated in the copolymer microcapsules had better cellular growth and proliferation behaviors, and could produce insulin under glucose stimulation." (PMID 35268787, 2022). "Other studies showed that the treatment with concentrations of sodium arsenite up to 2 μM in pancreatic islets from C57BL/6 mice, or RINm5F insulinoma cells attenuate GSIS without affecting insulin synthesis." (PMID 35651975, 2022). "The insulinomas secrete excessive insulin because the negative feedback mechanism that is initiated by falling blood glucose levels is disrupted in the neoplastic β-cells." (PMID 36288153, 2022). "In contrast to our data, it has been shown that overexpression of Exoc6 in mouse insulinoma βtc6 cells did not affect insulin secretion." (PMID 35336762, 2022). "While not definitive, the insulin secretion response and gene expression profile of the clusters produced in this study is not consistent with that of insulinomas." (PMID 35769100, 2022). "We then assessed rat insulinoma INS-1 cells, a highly secretory cell type that secretes insulin." (PMID 36325988, 2022). "Studies in insulinoma and CHO cells, revealed different potencies of the two peptides, and moreover, stimulation of insulin secretion by TLQP-62 in insulinoma cells was not blocked by the C3aR1 antagonist SB290157." (PMID 34626205, 2021). "Transcriptional upregulation of SSTR2 has also been shown with physiological factors such as insulin and growth hormones in liver cells of rainbow trout and it has been correlated with octreotide-induced overexpression of miR-16-p in INS-1 rat insulinoma NET cell line." (PMID 33435224, 2021). "Four of these seven (57%) patients with malignant insulinomas had originally non-functioning tumors, which later transformed into insulin-secreting lesions, which have been described in detail elsewhere." (PMID 33927695, 2021).
insulinoma (continued). "Collectively these data demonstrate that 48% of PanNETs generated in the INS-p25OE model are potential insulinomas and 52% do not produce elevations in the serum hormones analyzed and are likely non-functional." (PMID 34862365, 2021). "The insulinoma most certainly modified his diabetic control, such that he did not need either oral hypoglycemic agents or insulin." (PMID 34583764, 2021). "NIT-1 is another pancreatic β-cell line that was established from the insulinomas developed in transgenic, nonobese, diabetic mice, harbouring a hybrid rate insulin-promoter/SV40 large T-antigen gene." (PMID 34940547, 2021). "The inhibition of β cells’ insulin secretion may be explained by the choice of INS-1 cells, which were isolated from a rat insulinoma." (PMID 34577036, 2021). "Congenital hyperinsulinism (CHI) is a group of disorders that cause persistent hypoglycemia due to congenital excess secretion of insulin; it does not include acquired conditions such as insulinoma, iatrogenic hyperinsulinemia, or dumping syndrome." (PMID 34497584, 2021). "Although the non-standard insulin production in the permanent insulinoma-derived β-cell lines is well known, the actual lack of Zn2+ in their storage granules was unexpected." (PMID 33081637, 2020). "Earlier in vitro studies showed that FTO overexpression in MIN6 (mouse insulinoma) cells significantly inhibited insulin secretion in the presence of glucose, but did not affect insulin expression." (PMID 32747736, 2020). "In isolation, these events would predict that INS gene expression should be low or absent in insulinomas." (PMID 33060578, 2020). "Calcium stimulates release of insulin from hyperfunctioning, abnormal beta-cells found in insulinomas, but not from normally functioning beta-cells of the pancreatic parenchyma." (PMID 32992761, 2020). "The pathophysiological background of this test is based on the observation that calcium stimulates the release of insulin from hyperfunctional beta cells (i.e. insulinomas) but not from normal beta cells." (PMID 31951592, 2020). "The process of tumour detection involved biochemical screening tests including gastrin, glucose, insulin, chromogranin-A, pancreatic polypeptide, glucagon, vasointestinal polypeptide, prolactin and IGF-1 to assess for gastrinoma, insulinoma, enteropancreatic and anterior pituitary tumours." (PMID 31797261, 2020). "After treatment, the insulin sensitivity of insulinoma subjects was not significantly different from healthy control subjects." (PMID 32326226, 2020). "In summary, BON and QGP cells express only few miRs specific to insulinomas or mature/functional β-cells and, if present, transcript levels are low, which is consistent with the lack of INS expression in both lines." (PMID 32183367, 2020). "Analogous experiments were performed in Ins-1 rat insulinoma cells, to confirm that the observed interactions were not species-specific, and revealed that ERp29 co-precipitates with (Pro)Insulin." (PMID 32433667, 2020). "The Mayo Clinic conducted a study to differentiate between insulinoma and islet hyperplasia by including 42 patients with insulinoma and 74 patients with islet hyperplasia and performing ASVS to observe insulin elevation after calcium gluconate." (PMID 31743337, 2019). "However, insulin release in INS-1 832/13 cells, another rat insulinoma cell line, seems to be resistant to FCCP-induced proton leak." (PMID 31366145, 2019). "Insulinoma and islet cell hyperplasia differ in that neoplasms are absent from islet cell hyperplasia, but both secrete insulin, and surgery is indicated." (PMID 31743337, 2019). "In parallel, we recently demonstrated that one such inhibitor, ORY-1001, could enhance expression of insulin, MAFA, NEUROD, and GK in the insulinoma INS-1E cell line." (PMID 31072002, 2019).
insulinoma (continued). "Insulinomas are small, rarely metastatic tumors that secrete high amounts of insulin, and nonfunctioning PanNETs are larger tumors that are frequently metastatic but that do not secrete hormones." (PMID 30796198, 2019). "In mouse insulinoma (MIN6) cells, a specific inhibitor of CDK5 raised insulin secretion." (PMID 31822470, 2019). "Normal insulin levels therefore do not rule out the disease because absolute insulin levels are not elevated in insulinoma patients." (PMID 32009878, 2019). "The depletion of SIRT4 in insulinoma cells could activate GDH, thus increasing amino acid-stimulated insulin secretion." (PMID 30666234, 2018). "Initially, we performed magnetic resonance imaging and endoscopic ultrasonography of the pancreas to rule out insulinoma or other extrapancreatic tumors, which would not justify the high levels of anti-insulin antibodies observed in our case." (PMID 30462811, 2018). "The LC/MS data obtained from the two glucagonoma cases (Case 1 pre‐ and post‐treatment, and Case 2), an insulinoma (Case 3) and 62 control samples from healthy individuals were interrogated for glucagon, CHGA, CHGB, SCG2, insulin, c‐peptide, and the internal standard bovine insulin." (PMID 29857350, 2018). "Clarification of this issue would be facilitated by a similar comparison of insulinomas to other benign PNETs that do not overproduce insulin." (PMID 28974674, 2017). "The inhibition of insulin secretion from rat islets by 9-phenanthrol is consistent with the roles of the TRPM4 channel in mediating electrical activity and insulin secretion that has been demonstrated in several rodent insulinoma cell lines." (PMID 29098165, 2017). "An insulinoma was considered but a 24-hour fast was not performed given a low probability of this diagnosis with normal insulin levels." (PMID 29721512, 2017). "The MIN6 cell line, which was established from an insulinoma of a transgenic mouse expressing the SV40 T antigen in pancreatic β cells, secretes insulin in response to physiological stimuli and is a useful tool for studying the mechanisms of insulin secretion." (PMID 26986842, 2016). "Mouse insulinoma cell line (MIN6), isolated mouse pancreatic islets and human islets were starved for 24 hours in 0.1% serum and then stimulated for 24 hours with 100 nM insulin." (PMID 27526875, 2016). "Betulin potentiated insulin-stimulated glucose uptake by increasing PPAR-γ activities in 3T3-L1 adipocytes, whereas oleanolic acid enhanced glucose-stimulated insulin secretion and cell proliferation in Min6 insulinoma cells." (PMID 26884795, 2016). "We ruled out the possibility of exogenous administration of insulin or other anti-diabetic drugs, insulinoma and insulin autoimmune syndrome." (PMID 25918682, 2015). "The plasma insulin increase upon ABA administration was expected, based on the in vitro effect of ABA on insulinoma cells and on murine and human β-cells: exogenous ABA, added at concentrations in the low nM range, stimulated insulin secretion both in the presence and absence of glucose." (PMID 26488296, 2015). "On the other hand, several studies reported the beneficial impact of resveratrol (RSV) on insulin secretion and how this compound potentiates glucose-stimulated insulin secretion (GSIS), not only in rat insulinoma cell lines (INS-1E), but also in isolated human islets." (PMID 25774684, 2015). "On the other hand, a Brs3 agonist promoted insulin secretion in both rodent insulinoma cell lines and in islets isolated from wild-type but not Brs3 mutants." (PMID 26020940, 2015). "Based on these findings, we ruled out the possibility of exogenous administration of insulin or other anti-diabetic drugs, insulinoma and insulin autoimmune syndrome." (PMID 25918682, 2015). "In addition, treatment of MIN6 (mouse insulinoma cell line) and isolated human islets of Langerhans with Om Santal Adivasi extract (OSA), a high-molecular-weight leaf extract, stimulated insulin secretion." (PMID 26587047, 2015).
insulinoma (continued). "Normal insulin levels do not exclude the possibility of the disease, as the absolute insulin levels are not elevated in all patients with insulinoma." (PMID 25202394, 2014). "Our preliminary study demonstrated that IG-1 inhibited glucose-induced insulin secretion in Min-6 insulinoma cells (data not shown)." (PMID 24971987, 2014). "Our patient did not have an insulinoma, because his serum insulin concentration was reduced during hypoglycemic attacks." (PMID 24307956, 2013). "In mouse insulinoma (MIN6) cells stimulated with glucose, miR-30d enhances insulin gene transcription, indicating that miR-30d could be responsible for downregulating insulin transcription repressors." (PMID 24369540, 2013). "This test did not localize a region of insulin hypersecretion, and thus was not consistent with a diagnosis of insulinoma." (PMID 22937294, 2012). "We investigated whether TLR4 is present in β-cells purified from freshly isolated human islets and confirmed the results using MIN6 mouse insulinoma cells, by analyzing the effects of TLR4 expression on cell viability and insulin homeostasis." (PMID 21356084, 2011). "A set of experiments in which mouse insulinoma cells (β-TC3) were cultured for 24 h with the protein showed that purified TAT-MafA increased insulin expression by about 15-fold (data not shown)." (PMID 21857924, 2011). "Previous studies suggested that β2-syntrophin is phosphorylated at multiple sites in rat insulinoma INS-1 cells and that dephosphorylation following stimulation of insulin secretion weakens its binding to ICA512 and the anchoring of insulin granules to microfilaments." (PMID 20886068, 2010). "In order to ensure that the observed reduction of insulin in the insulinoma cells was not due to the known effects of pericentrin depletion on cell cycle progression, we repeated our experiments in quiescent primary islets." (PMID 20676397, 2010). "Since insulinoma cells are typically cultured in high glucose media (25mM) and have high basal insulin secretion, a series of low non-stimulatory glucose incubations are necessary prior to glucose stimulation." (PMID 20676397, 2010). "It is important to note the fact that the barely detectable intracellular insulin levels is in accordance with the description of insulinomas as having poor or almost non-existent capacity for insulin storage, thus presenting no positive staining for insulin." (PMID 19545371, 2009). "To test whether these CpG sites have a specific methylation pattern in pancreatic beta cells, we compared the insulin promoter CpG methylation pattern in pancreatic beta cells with various other tissues and with the NIT-1 mouse insulinoma cell line." (PMID 19742322, 2009). "In agreement with the very well characterized excessive and/or uncontrolled insulin release, displayed by insulinomas and nesidioblastosis, none of our cell cultures presented glucose-induced insulin secretion." (PMID 19545371, 2009). "Next we used MIN6c4 insulinoma cells, known to endogenously express GPR40 to study whether ROZ interacts with the reported FFA-stimulated activation of PLC via GPR40 in insulin-producing cells." (PMID 18478115, 2008). "Although fasting tests confirmed autonomous insulin secretion in our patient, angiography finding of a vascular area in pancreas did not indicate that the EUS visualized cystic tumour in the pancreas was an insulinoma." (PMID 18086310, 2007). "Although fasting tests confirmed autonomous insulin secretion in our patient, the angiography finding of a vascular area in the pancreas did not indicate that te EUS visualized cystic tumour in the pancreas was an insulinoma." (PMID 18086310, 2007). "Treatment with brefeldin A blocked both basal and L-arginine stimulated insulin secretion in Hepa1-6 cells, but did not effect the secretion of insulin from MIN6 insulinoma cells, which occurs via regulated exocytosis from insulin granules." (PMID 17941991, 2007).